IFNG (interferon gamma)
Diseases named in the same sentence as IFNG in open-access papers (continued):
Sharing a sentence is not in itself a finding about the gene and the disease.
infection (continued). "Under the infection and allergic irritation, C57BL/6 mice are dominated by Th1 immune response and IFNγ, while Th2 immune responses were easier to be triggered in Balb/C mice." (PMID 37691828, 2023). "The adaptive response characterized by T-helper 1 (Th1) activation produces cytokines such as interferon-gamma (IFN-γ), interleukin-2 (IL-2), and tumor necrosis factor-alpha (TNF-α), which help to control the infection." (PMID 37375511, 2023). "Infection of BMDCs with EBs opsonized with male IgG enhanced expression of chemokines CXCL1, CXCL2, CXCL5 and pro‐inflammatory cytokines TNF, IL1β and IFNγ compared to uninfected or non‐opsonized controls." (PMID 38441219, 2023). "Infection with SARS-CoV-2 elicits the activation of CD4+and CD8+ cytolytic T lymphocytes, both of which induce the production of interferon-gamma (IFN-γ)." (PMID 37855635, 2023). "For example, the recent evidence that BCG induced IFNγ can protect mice from SCV2 challenge raises the question of whether the cytokine could be used intranasally to protect subjects at high risk of infection possibly with less risk of toxicity than Type I IFN." (PMID 37744331, 2023). "Vaccination with QuilA®-Coxevac® skewed the transcriptional gene expression induced by infection towards an increased expression of CD8, NRC1 and the Th1 cytokine IFNγ in spleen, corroborating the previous results of cell phenotyping and IFNγ production." (PMID 36788233, 2023). "The highest frequency of each population was observed at 1 month post-infection, (Median: 0.0093%; 0.012%; and 0.018% for IL2 + / IFNγ-; IFNγ + /IL2-; and IL2 + /IFNγ + CD4 + T cells, respectively)." (PMID 37974069, 2023). "In the context of aerosol infection with high doses of M. tuberculosis HN878, IFNγ appears to be partly dispensable." (PMID 37383236, 2023). "Mechanism of EGCG as an anti-infection by L-pneumophila bacteria due to nicotine is through macrophages that produce tumor necrosis factor alpha (TNF-α) and interferon gamma (IFN-γ)." (PMID 37346971, 2023). "The expression of IFNγ and IL-2 in PBMC co-cultured with KMeC infected with rNDV-cIFNγ was higher than in infection with rNDV-GFP." (PMID 37022566, 2023). "The numbers of Ifnγ+ NK, NKT, and γδ T cells did increase significantly at either day 5 or day 10 post-infection but these changes were small." (PMID 37842651, 2023). "In further analysis of infection-naïve individuals by ICS, lower CD4+ and CD8+ IFNγ and TNF responses to Delta S peptide pools were found among cases compared to controls." (PMID 37655880, 2023). "Together, these data suggest that IRF1 contributes to ZBP1-mediated PANoptosis in response to stimulation with IFNγ plus KPT-330 and infection with IAV by regulating ZBP1 expression." (PMID 37557956, 2023). "The increased influx of macrophages to the site of infection was in agreement with the robust Th1 response and CD4+IFNγ+-producing cells, which function as major macrophage activators, detected in anti-Gr1-treated mice." (PMID 36776848, 2023). "Post-infection high anti-S RBD antibody levels were observed in LTR, and healthy controls (HC), while the cellular immune response, assessed by interferon-gamma release assay (EUROIMMUN), was significantly lower in LTR compared with HC (p < 0.001)." (PMID 36851510, 2023). "IHC analysis also demonstrated significantly increased IFNγ levels in the lungs of MFD-fed infected mice compared to RD-fed infected mice during both the acute and chronic stages of infection." (PMID 36676177, 2023). "Neurons in the cell body compartment of microfluidic devices were directly treated with IFNα-14, IFNβ, IFNγ, or IFNλ-3 for 24 h prior to HSV-1 or mock infection." (PMID 37655893, 2023). "To understand the association between SHIV-specific Th1 cells and protection in this study, we stratified vaccinated animals into two groups (low vs high) based on median IFNγ + CD4 T cell response and compared the rate of infection." (PMID 37553348, 2023).
infection (continued). "Following MHV68 infection of Ifnar1-/- mice, the expression of TNF-α, IFNγ, and IL-2 is decreased in antigen-specific CD8+ T cells, showing clear hallmarks of T cell exhaustion in the absence of type I IFN signaling." (PMID 37065193, 2023). "Recruitment of total ubiquitin, p97/VCP, ANKRD13A, and UBXD1 at 2 h was determined at the PV in cells pre-stimulated with IFNγ and then treated for 2 h with the E1 enzyme inhibitor, PYR41, prior to infection with Tg type II Pru." (PMID 37975677, 2023). "Furthermore, many individuals that do develop a T cell IFNγ response against Mtb may eventually eradicate infection, as the incidence of active TB is quite low amongst IGRA+ individuals (usually less than 5%) even when their immune systems are potently immunosuppressed or ablated." (PMID 38011264, 2023). "These conditions resemble our CFU results of IFNγ post-stimulated BMDM, as we observed an impaired infection control by these macrophages." (PMID 37190073, 2023). "By comparing the effects of maternal IFNγ injection with maternal T. gondii infection, we reveal that the effects of IFNγ treatment mimic some aspects of the fetal HSC response to infection." (PMID 37259639, 2023). "In a recent report for Rickettsia parkeri, another closely related obligate intracellular pathogen, it is found that infection control is mediated by both antiviral-like and antibacterial responses, involving IFN-I and IFNγ, respectively." (PMID 38091346, 2023). "As IFNγ has been widely implicated in EM and we observed an increase of the expression of this cytokine in the BM of M. tuberculosisHN878-infected mice, we sought to investigate whether its presence was required for the EM observed in the C57BL/6 model of infection." (PMID 37383236, 2023). "Levels of interferon-gamma (IFNγ), TNF and interleukin 6 (IL-6) similarly peaked in BALF of control mice 5 days after infection, and were likewise decreased and delayed in Gabra1-IRES-cre; Ptger3flox mice." (PMID 36890237, 2023). "In a subset of matched infection-naïve cases and controls, vaccine breakthrough cases had lower CD4+ and CD8+ IFNγ and tumor necrosis factor (TNF) responses to Delta S peptides compared with controls." (PMID 37655880, 2023). "Splenic IAV-specific CD4 T cells were also activated by the re-infection, increasing their expression of CD69 and ICOS, although the expression of Ifnγ was equivalent to that in memory animals." (PMID 37842651, 2023). "Natural killer (NK) and innate lymphoid cells contribute innate sources of IFNγ, whereas CD4+ Th1 cells and CD8+ T cells are major producers of this cytokine later in infection." (PMID 38086794, 2023). "Upon infection, the immune system triggers the release of proinflammatory cytokines, such as tumor necrosis factor-alpha (TNF-α), interleukin-1 (IL-1), and interferon-gamma (IFN-γ), which are intended to suppress parasite growth and proliferation." (PMID 37670044, 2023). "Next, we evaluated the presence of soluble polypeptides for IFNγ, IL-1β, IL-4, IL-6, IL-8, IL-10, CXCL10, and TNFα in serum of animals following infections with Att-S74-T3Bo and Vir-S74-T3Bo." (PMID 36466866, 2022). "The different biological systems secrete different amounts of interferons upon infection, and AECII are the most potent producers of IFNγ RNA and protein." (PMID 36446841, 2022). "Its upregulation is mediated by proinflammatory cytokines, such as interferon gamma (IFN‐g) and granulocyte colony stimulating factor (G‐CSF), which are produced in large quantities in response to infection or tissue injury." (PMID 36111748, 2022). "Even though we found decreased numbers of splenocytes and α-CD3 induced IFNγ+ responses in chronically LCMV infected mice, a similar cross-reactive NP205-specific T cell response was detectable after PICV infection, compared to LCMV+PICV infected mice." (PMID 36298848, 2022).
infection (continued). "Infection with UT127 led to the expression of the M1 markers IL12RB, IL2RB, and IFNG, concomitantly expressing the M2 markers CTLA4, IL10, and PLXNB2." (PMID 35163725, 2022). "In the cerebellum, expression of IFNγ and IL12 decreased at days 60 and 120 post-infection, and TNFα remained high." (PMID 35216083, 2022). "Higher NK cell abundance correlated with increased pulmonary IFNγ levels in BALB/c mice, whereas Il1b was slightly higher in C57BL/6 animals 3 days after infection." (PMID 35023830, 2022). "Corresponding to BECs, IFNγ increases LEC activation, while IL-10 downregulates LEC activation upon infection." (PMID 35789215, 2022). "The IFN-γ signaling pathway in intestinal glial cells is critical for intestinal homeostasis, and the IFNγ -EGC-CXCL10 axis plays a key role in immune response and tissue repair after infection." (PMID 35620725, 2022). "The DST reliably identifies bTB-infected animals in experimental challenge models and in natural infection settings, and differentiated these from animals immunized with a single dose of BCG in both skin tests and interferon-gamma release assay (IGRA)." (PMID 35498753, 2022). "These alterations in the kinetics of monocytes, neutrophils, and CD4+ T cells coincided with a significant increase in serum concentration of TNFα, IFNγ, CXCL10, and IL-10 early after infection." (PMID 36466866, 2022). "There was also a significant decrease in fluorescent signal in IFNγ alone, or in co-cultures with M1 macrophages in ALI medium or IMM, compared to infection in ALI medium alone." (PMID 36228018, 2022). "Presently, two types of tests are commercially available to test children for infection with Mtb: the tuberculin skin test (TST) and interferon-gamma release assay (IGRA)." (PMID 35215101, 2022). "The increase in CD4+IFNγ+ T cells and the decrease in CD4+IL-4+ T cells observed at the site of infection correlated with decreased parasite burden in the lesion of Mrp8;Metfl/fl mice." (PMID 35041723, 2022). "Thence, the enriched “Positive regulation of interferon-gamma production” and “Inflammatory mediator regulation of TRP channels” regulated by differentially expressed miRNAs in the present study might be the key driver to causing the exacerbation of CV-A10 infection." (PMID 35864512, 2022). "Based on the observation of IFNγ, producing T-cell responses to SARS-CoV-2 immunization through natural infection or vaccination, the IGRA was introduced as an attractive alternative method of cellular immunity assessment." (PMID 36146624, 2022). "Spike S1 subunit-specific IFNγ and tumour necrosis factor (TNF) production and S2-specific TNF responses in CD4+ T cells were higher in previously infected individuals than in infection-naive individuals." (PMID 34778853, 2022). "The infection cytokines produced by interleukin (IL-6, IL-8, IL-1β), tumor necrosis factor-alpha (TNF-α), and interferon-gamma (IFN-γ) are all accompanied by a severe infection." (PMID 36421668, 2022). "When we assessed T-helper (Th) cell immunity, SARS-CoV-2-specific Th cells produced detectable amounts of IFNγ and TNF six weeks after the infection." (PMID 35062775, 2022). "Cells were left untreated or were pre-treated for 2 hr with 10 ng/mL interferon-gamma (IFN-γ), infected with Chlamydia (Ctr) at multiplicity of infection (MOI) 1 and lysed at 30 hpi for Western blot analysis (n=3)." (PMID 36155135, 2022). "The number of IFNγ+ CD4+ T cells was also higher in LY‐411,575‐treated lungs but similar in LNs when the infection was established after day 7 PI." (PMID 35603470, 2022). "Upon infection, HRV further exaggerated the secretion of IFNγ (P < 0.01), and enhanced TNFα (another Th1 cytokine) production (P < 0.01) in COPD cultures compared to HRV infected healthy cultures." (PMID 35280870, 2022). "Vaccinated macaques showed SIV-specific CD4+ T cells, as well as IFNγ-producing CD8+ T cells, in the early phases of infection." (PMID 36033843, 2022).
infection (continued). "A statistically significant increase in the fraction IFNγ-producing of DGKζ KO P14 CD8+ T cells compared to WT was seen on Days 7 and 10 post infection." (PMID 36846018, 2022). "It is widely accepted that CD4+ T helper 1 (Th1) cells, which express the cytokines interferon-gamma (IFN-γ) and tumor-necrosis-factor (TNF), play a major role during infection with Mtb." (PMID 36139450, 2022). "The cytokine Interferon-gamma (IFN-γ) plays a significant role in maintaining the action of both CTL and HTL during infection." (PMID 36284708, 2022). "Quantitative analysis revealed significant levels of the pro-inflammatory cytokines TNFα, IFNγ, and CXCL10 at day 6 after Att-S74-T3Bo infection compared to uninfected control animals." (PMID 36466866, 2022). "CD44 is also a marker of T cell activation, and similarly, significantly increased IFNγ+ and IL-17+ cells were present among CD4+CD44+ T cells from Mtb-HT1 infected mice at week 2 post infection." (PMID 35173157, 2022). "Leishmania antigen-stimulated peripheral blood lymphocytes also produce interferon gamma (IFN-γ) and tumor necrosis factor (TNF) in subclinical infection, but at lower levels than CL." (PMID 32830257, 2021). "We detected higher IFNγ, IFNα, and IFNβ levels in skin biopsies from iKIR-treated and infected mice than scrambled KIR-treated mice at day 3 post-infection." (PMID 33690673, 2021). "As observed for day 1 post infection, in the SIM group we observed increased percentage of multifunctional effector CD4 T cells expressing IFNγ/TNFα or IL-17/TNFα." (PMID 34925371, 2021). "Similar to the immune response in the acute phase of infection, TKO mice compared to WT mice showed a lower frequency of IFNγ producing CD8+ T cells." (PMID 33968021, 2021). "Infection is inferred from the presence of anti-mycobacterial immunoreactivity, as shown by a positive result in tuberculin skin test (TST) and/or interferon-gamma (IFN-γ) release assay (IGRA)." (PMID 33661925, 2021). "On the other hand, C. pseudodiphtheriticum 090104 was shown to inhibit secondary infection of S. pneumoniae in vivo probably by inducing elevated TNF-alpha and interferon gamma levels." (PMID 34529731, 2021). "In mice, several leukocyte populations expand during infection including NK and NKT cells followed later by CD4 and CD8 T lymphocytes and the immune response proceeds mostly through production of interferon gamma (IFN-γ), commonly produced by T lymphocytes." (PMID 34250067, 2021). "(A) Intracellular growth of Mtb inside resting or IFNγ-primed BMDMs treated with iFADS2 or with vehicle control, as determined by colony-forming unit (CFU) plating at the indicated days post infection." (PMID 34951591, 2021). "Surprisingly, the swIAV infection conversely affected the cell-mediated immune response (CMI) against the PRRSV, tending to enhance the number of MLV1-specific IFNg-SCs during the post-vaccination period." (PMID 33917103, 2021). "In both RMT and SBP P. chabaudi infections shown here, many lymphoid cell populations produce IFNγ in the first 7 days of infections, with CD4+ T cells comprising the greatest numbers and proportions by day 7 of infection." (PMID 34532703, 2021). "Iron loading prior to infection fostered bacterial burden and, unexpectedly, reduced differentiation of CD4+ T helper cells type 1 (Th1) and expression of interferon-gamma (IFNγ), a key cytokine to control infections with intracellular pathogens." (PMID 34108960, 2021). "This MΦ activation can be put down to the release of IFNγ by CD4+ T cells and again, as in the infection with O. tsutsugamushi, demonstrates that the T cell-derived IFNγ-MΦ axis, although essential for protection, has pathological side effects." (PMID 34452021, 2021). "Testing of splenocytes collected on day 8, 9, or 10 post-infection confirmed that stimulation with M195 and N198-206 (N198) peptides produced a significantly increased number of HMPV-immune splenocytes releasing IFNγ." (PMID 34675220, 2021).
infection (continued). "Suggesting low systemic response, the blood of mice trained 9 weeks contained lower levels of a broad range of cytokines (IL-1β, IL-6, IL-10, IL-12p40, IL-17A, IL-18, IFNγ, TNF, CCL2 and CXCL5) 2 days after infection with L. monocytogenes." (PMID 34603295, 2021). "At 6, 24, 48, and 72 h post infection, blood samples were collected, and the serum levels of 10 cytokines (GM-CSF, IL-1β, IL-6, IL-10, TGF-β1, IFNγ, IL-4, IL-8, IL-12p40, and TNF-α) were assessed." (PMID 33665221, 2021). "We compared the levels of interleukin 17 (IL-17), interferon gamma (IFN-γ), and transforming growth factor β1 (TGF-β1) in peripheral blood on days 14, 22, and 30 after infection." (PMID 34908455, 2021). "Chimeras were immunized with Lm-gB and treated with DT before Lm-gB challenge infection, and we monitored both LLO91–99/Kd and gB498–505/Kb Tet+ CD8+ TM cells for Ag-dependent chemokine (CCL3) and Ag-independent IFNγ production." (PMID 34516896, 2021). "Interferon gamma (IFN-γ) from NK cells and other immune cells infiltered at the infection sites is key to mucosal anti-C. parvum defense (22, –, 26)." (PMID 34488445, 2021). "Differently from HeLa cells and possibly due to infection-induced type-I IFN production, C. trachomatis infection significantly increased the IDO1 expression in IFNG-treated HL-60 cells compared to IFNG-only-treated cells." (PMID 34819931, 2021). "The data demonstrated that at day 1 post infection, the SIM group showed activated multifunctional vaccine-specific CD4 T cells (IL-17+/TNFα+ Th17 or IFNγ+/TNFα+ Th1 T cells) in the GT." (PMID 34925371, 2021). "Having shown that CNS infection leads to neuron death, and IFNγ was highly represented in multiple tissues of Optn−/− mice, we sought to understand the role of OPTN in necroptosis during infection." (PMID 34518549, 2021). "Naïve macrophages can be activated either classically into a proinflammatory M1 phenotype by IFNγ, TNF-α, and TLR ligands to defend against infection or into an anti-inflammatory M2 phenotype by IL-4 and IL-13 to aid in healing." (PMID 34539613, 2021). "Among the infection-induced genes, ido1 and tdo2 were found, but for robust protein-level induction of IDO1, the addition of IFNG was needed." (PMID 34819931, 2021). "A significant increase in IFNγ mRNA was found in the spleens of UPEC LT004 infected animals, compared to animals infused with PBS (sham-infection)." (PMID 34015044, 2021). "After 24 hr of infection, Mtb’s uptake of PA, OA, LA, and EPA was comparable in resting and IFNγ-activated BMDMs." (PMID 34951591, 2021). "In adult Xenopus, FV3 infection also induces a rapid response (as early as 1dpi) of type I IFN and Mx1 and 2, as well as pro-inflammatory and inflammatory-related genes (IFNγ, IL-1β, and TNF-α) in the kidney." (PMID 34675918, 2021). "In vivo studies with HSV-1 and WNV demonstrate the significance of specific cytokines (IFNγ and IL-1β, respectively) that modulate NSC responses during infection, and provide a crucial model for understanding the complexity of viral pathogenesis in the brain." (PMID 34452333, 2021). "Th1 effector cells, through the creation of interferon-gamma (IFN-γ), as a critical cytokine, along with tumor necrosis factor (TNF)-α and -β mediate protection against H. pylori, has contributed to the infection." (PMID 35083009, 2021). "Although the pre-treatment of cells with different IFN-I and IFN-III subtypes, as well as with IFNγ, has been shown to interfere with orthohantavirus replication, the question remains on the type of human IFN that is induced during orthohantavirus infection." (PMID 33478127, 2021). "IDO1 is induced by interferon gamma (IFN-γ), an innate immune cytokine that is stimulated in response to Ct infection." (PMID 33975934, 2021). "We performed IFNγ-ELISPOT assays using fresh PBMC from cy0428 and cy0575 using these two peptides as stimuli at days 21 or 28 post-infection." (PMID 34855793, 2021).